CD160 (CD160 molecule)
Diseases named in the same sentence as CD160 in open-access papers (continued):
Sharing a sentence is not in itself a finding about the gene and the disease.
cancer (continued). "Since age has impact on DNA methylation patterns, we next evaluated the relationship between the methylation levels of CD160, ISYNA1 and RAD51B and age in 272 sporadic BC cases and 272 cancer-free female controls combining validation I and validation II." (PMID 35812748, 2022). "Differential expression of CD160, ISYNA1 and RAD51B has been correlated to the clinical characteristics in various types of cancer." (PMID 35812748, 2022). "We then further investigated the potential role of CD160 in AML pathogenesis and progression by studying the clinical outcomes of cancer patients in the TCGA database." (PMID 33239726, 2021). "In previous studies, CD244 has already been shown to be co-expressed on CD8+ T-cells with other immunoregulatory receptors, including PD-1, CD160, CTLA-4, and TIM-3 in both mouse cancer models and patients with cancer." (PMID 34944879, 2021). "Reduction in the percentage of CD4+ T cells expressing PD-1, CD73, CD160, or LAG3 by LYC-54143 was observed in differentiated human Type 17 T cells using PBMCs from cancer patients as well as healthy donors." (PMID 28123897, 2016). "Additionally, USP37 demonstrated a significant positive relationship with ADORA2A, CD160, TNFSF15 and NRP1 across the majority of cancers." (PMID 40926837, 2025). "Furthermore, the expression of GPX4 was closely associated with MHC molecules, immune activation genes, and immunosuppressive genes such as HLA-A, HLA-B, CD160, TNFRSF18, TNFRSF4 and CD276 in most cancer types." (PMID 41142608, 2025). "CD160, ISYNA1 and RAD51B have been involved in the development of various types of cancer." (PMID 35812748, 2022). "To comprehensively investigate the immunoinhibitory pathways in T cells, we used FACS to analyze the surface expression of eight IRs (PD-1, Tim-3, BTLA, KLRG-1, TIGIT, 2B4, CD160, and CTLA-4) on T cells from peripheral blood and tumors isolated from 131 cancer patients." (PMID 31709176, 2019). "Furthermore, there is a notable lack of literature regarding CD160 gene variation and its potential relevance to cancer." (PMID 38999968, 2024). "ENST00000311534 was significantly correlated with HMGB1, ENST00000326094 was significantly correlated with BTN3A1, CD160, TGFBR1, and IL6R, and ENST00000375991 was significantly correlated with CD276, ENTPD1, HMGB1, TLR4, KDR, and TGFBR1 among these 33 immune genes in more than 20 cancer types." (PMID 39766805, 2024). "Analysis of co-expression of two and more exhaustion markers shows that combination of BTLA and CD160 with or without LAG-3, conversely to other markers, show the maximum of downregulation in cancer samples." (PMID 39234236, 2024).
infection (25 papers, 2012 to 2025). The state of being infected such as from the introduction of a foreign agent such as serum, vaccine, antigenic substance or organism. "Initially, murine studies revealed that chronic lymphocytic choriomeningitis virus clone 13 (LCMV-13) infection caused an up-regulation of PD-1 and other inhibitory receptors, like CD160, 2B4, and Lag-3, which cooperate to mediate CD8+ T cell dysfunction." (PMID 25032686, 2014). "The aggregation of multiple immune cell types with Cd160+Cd8+ T cells during infection can be observed in Stereo-seq slides." (PMID 39414763, 2024). "Ccr7+Ido1+ DCs, Cd160+Cd8+ T cells, and Tnfrsf4+Cd4+ T cells all increased after infection, and were viral RNA-positive, suggesting direct involvement of these immunity hubs against SARS-CoV-2 infection." (PMID 39414763, 2024). "The reductions in infiltrating leukocytes in the BTLA−/− LIGHT−/− and CD160−/− LIGHT−/− mice indicate that multiple HVEM binding partners play roles in promoting leukocyte infiltration in the cornea following infection." (PMID 32398314, 2020). "Because mice are able to naturally clear PyNL parasite, we also analyzed CD160 expression on CD8+ T cells after resolution of the infection (d 20 p.i.)." (PMID 30483269, 2018). "As shown for antigen-specific responses, total CD8 T cells upregulated CD160 expression only during the chronic stage of infection." (PMID 22916009, 2012). "Interestingly, infection of macrophages with live CD160 and NAP1/BI/027 strains or incubation with CDH plus NAP1/BI/027 secretome induced similar endocytic levels compared to CDH." (PMID 38249298, 2023). "Moreover, EGR2 loss diminished the expression of multiple inhibitory receptors (PD-1, 2B4 and TIM3) within tetramer+ CD8+ T cells over the course of infection, while CD160 and LAG3 were either unchanged or even elevated within cKO cells." (PMID 33986293, 2021). "CD160 may only be expressed on a subset of exhausted CD8+ T cells late during infection making it a player in sustaining the persistent infection." (PMID 34696381, 2021). "However, an aggravated T cell mediated pathology upon infection with PbA in CD160−/− mice suggests a co-inhibitory function of CD160." (PMID 30483269, 2018). "In addition to TIGIT, a number of other inhibitory receptors linked to immune dysfunction, such as PD-1, CD160 and 2B46, 7, 9, 10, 12, 13, are expressed on HIV-specific CD8+ T cells during the course of infection." (PMID 28084312, 2017). "Importantly, HIV and CMV-specific CD8 T cells expressed similar levels of CD160 in the acute phase of infection." (PMID 22916009, 2012). "A possible explanation for these findings is that CD160+ cells may be preferential targets for infection and depletion during ART, which would explain the strong negative association between the frequency of CD160+ CD4+ T cells and a putative marker of persistent viral replication." (PMID 27415008, 2016). "To determine if the differences in ocular disease pathogenesis were a result of differences in viral replication early in infection, we measured viral titers in the tear film at 1, 3, and 5 dpi in BTLA−/− LIGHT−/−, CD160−/− LIGHT−/−, and CD160−/− BTLA−/− mice." (PMID 32398314, 2020). "Expression of the activation and effector function markers CD69, CD160, CD44, and CD62L were analyzed at day 6 post infection (p.i.)." (PMID 28261571, 2017). "As early as day 8 post-infection, D2B6F1 mice exhibited reduced PD-1 and CD160 expression on their CD8 T cells." (PMID 28715493, 2017). "To determine the extent of CD8 T cell exhaustion in D2B6F1 and BCF1 mice, we examined PD-1, CD160 and LAG-3 expression and epitope-specific IFN-γ production during Cl-13 infection." (PMID 28715493, 2017). "Transcriptional networks have been related to CD8+ T cell exhaustion after LCMV-13 infection in mice, and recently also in HIV-specific CD8+ T cells specifically expressing PD-1 and CD160." (PMID 25032686, 2014).
infection (continued). "Taken together, these results showed a dynamic evolution of the frequency and distribution of CD160 and/or PD-1 expression on HIV-specific CD8 T cells during infection." (PMID 22916009, 2012). "Herein we report that another negative regulator of T cell activation, CD160, was also upregulated on HIV-specific CD8 T lymphocytes mostly during the chronic phase of infection." (PMID 22916009, 2012). "We assessed the frequencies of CMV, EBV and HIV-specific CD8 T cells expressing CD160 and/or PD-1 in 5 HIV-infected subjects during AHI (<3 months on infection) and CHI (>6 months of infection)." (PMID 22916009, 2012). "We therefore analyzed the expression and function of CD160 and PD-1 on CMV and HIV-specific CD8 T cells during different stages of infection and identified 4 functionally distinct subsets of CD8 T cells (CD160−PD-1−, CD160−PD-1+, CD160+PD-1−, CD160+PD-1+)." (PMID 22916009, 2012). "Furthermore, several additional transcripts associated with innate effector cell function were upregulated throughout acute infection, compared to pre-infection, including NKG7, KLRD1, EOMES, CD160, SLAMF5, and IL12RB1." (PMID 31937782, 2020). "For instance, CD69, CD160, CD44, LAG3, and CTLA-4 expression on day 7 is unaffected in the absence of AT1R following immunization, but here we showed that the expression of these proteins is reduced by day 6 following infection." (PMID 28261571, 2017). "Interestingly, CD160, a binding partner of herpes virus entry mediator (HVEM), has been found to be a negative regulator of T cell activation and is upregulated on exhausted CD8+ T cells during LCMV Cl 13 infection." (PMID 34696381, 2021). "By day 30 post-infection, virus was cleared from both LCMV Arm-infected mice and Cl-13-infected D2B6F1 mice and PD-1 and CD160 were no longer expressed on the CD8 T cells." (PMID 28715493, 2017).
immune disease (4 papers, 2017 to 2022). "In summary, our study demonstrated that CD244 instead of CD160 is an important immune regulator involved in the process of T cell aging, making it an effective therapeutic target to improve age-related immune disorders and comorbidities." (PMID 35386693, 2022).
bacterial infections (1 paper, 2023). "Thirdly, replication for other bacterial infections is needed to confirm the suitability of CD160 as a marker for NK cell memory across different diseases." (PMID 37520720, 2023).
metabolic disorders (1 paper, 2022). "CD244+CD160- CD8+ T cells displayed the increased activity of β-GAL, higher production of cytokines, and severe metabolic disorders, which were characteristics of immune aging." (PMID 35386693, 2022). "Moreover, only CD244+CD160- CD8+ T cells were identified as senescent population, manifested by increased activity of β-GAL, higher production of cytokines, and severe metabolic disorders." (PMID 35386693, 2022).
CD160 also shares sentences with these, for which no sentence is quoted: colon carcinoma (3 papers); gastric cancer (3); autoimmune thyroid disease (2); colorectal cancer (2); Diabetes (2); esophageal cancer (2); pancreatic cancer (2); triple-negative breast carcinoma (2); viral diseases (2); acquired aplastic anemia (1); active tuberculosis (1); adenocarcinoma (1); asthma (1); atopic dermatitis (1); B-cell neoplasm (1); bladder cancer (1); Chagas disease (1); clear cell renal carcinoma (1); congenital heart disease (1); Crohn disease (1); dengue (1); dermatitis (1); diffuse large B-cell lymphoma (1); glioblastoma (1); Hashimoto thyroiditis (1); hematological malignancies (1); hepatitis B virus infection (1); hyperuricemia (1); hypothyroidism (1); Immunodeficiency (1).
A further 17 diseases each share a sentence with CD160 in 1 paper.